CHEK2 (checkpoint kinase 2)
Diseases named in the same sentence as CHEK2 in open-access papers (continued):
Sharing a sentence is not in itself a finding about the gene and the disease.
hereditary cancer (36 papers, 2006 to 2025). Malignant neoplasms occurring in families at a rate greater than that expected by chance and caused by germline mutations in a specific gene. "We identified 42 probands with CHEK2 p.I157T at the University of Utah who underwent hereditary testing after referral for solid tumor hereditary cancer risk assessment." (PMID 40335619, 2025). "This is in line with the difficulties classifying CHEK2 variants, having been recognised as one of the genes with more conflicting interpretations in hereditary cancer." (PMID 40177144, 2025). "A recent retrospective study in patients who underwent hereditary cancer multigene panel testing identified 2508 carriers of a pathogenic CHEK2 variant." (PMID 35101071, 2022). "Routine genetic testing of CHEK2 is now included in diagnostic NGS panels targeting various hereditary cancers, and CHEK2 ranks among genes with the highest frequency of germline mutations." (PMID 33322746, 2020). "Collecting research information on CHEK2 mutations, however, serves to advance our understanding of the contribution of this gene to hereditary cancer risk." (PMID 22114986, 2011). "In this context, it is important to characterize and explore the prevalence of CHEK2 variants among patients with cancer or hereditary cancer risk in Türkiye as these data will inform the counseling and care of patients or individuals with P/LPs vs. low-risk variants in CHEK2." (PMID 39594831, 2024). "In addition, her CHEK2 mutation (AF: 69%) was confirmed to be germline by Ambry Genetics (Aliso Viejo, CA) hereditary cancer plasma genotyping assay." (PMID 36061833, 2022). "We concluded that the homozygous CHEK2 variant was contributory in this case of familial cancer." (PMID 27900359, 2016). "Although heterozygous CHEK2 mutations were previously denied as the cause of multiple familial cancers, these data suggest the possibility that homozygous inactivation of this protein may lead to multi-organ cancer." (PMID 27900359, 2016). "We observed evidence of a HM phenotype in patients and families with P/LP CHEK2 variants in a HHM cohort, as well as a separate validation cohort that was tested for solid tumor hereditary cancer risk." (PMID 40335619, 2025). "Among these, CHEK2 and PALB2, two of the genes involved in the homologous recombination pathway, have been associated with an increased risk of breast and other cancers, and are included in the NCCN guidelines for hereditary cancer risk assessment." (PMID 35456488, 2022). "Along with BRCA1 and BRCA2, multiple HRR genes, including ATM, BARD1, BRIP1, CHEK2 (encodes CHK2), MRE11A, PALB2, RAD50, RAD51C, and RAD51D, are also implicated in hereditary cancer risk and are recently considered new potential biomarkers in patients with non-gBRCA HRR gene mutations." (PMID 34900718, 2021). "The possible involvement of genes like BRCA1, BRCA2, CHEK2, and POT1, which are known to play a role in other hereditary cancers, could lead to new knowledge of UM, especially in family cases." (PMID 39926282, 2025). "The majority of germline alterations were unknown or benign, with the exception of one alteration each in familial cancer genes MUTYH, CHEK2, and FANCL, as well as one germline alteration in ID3." (PMID 36232827, 2022). "Thus, it may be possible to selectively target familial cancers as the non-cancerous (i.e. normal) cells are expected to harbor a single wild-type copy of BLM or CHEK2, and produce sufficient protein to render these cells resistant to a SL attack." (PMID 26318585, 2015).
Lynch syndrome (34 papers, 2014 to 2025). An autosomal dominant hereditary neoplastic syndrome characterized by the development of colorectal carcinoma and a high risk of developing endometrial carcinoma, gastric carcinoma, ovarian carcinoma, renal pelvis carcinoma, and small intestinal carcinoma. "Participant A’s cancers are all likely caused by the Lynch syndrome variant; the CHEK2 variant is less likely to impact on her phenotype." (PMID 34711244, 2021). "The genes with the highest prevalence of P/PV variants included CHEK2 (26%), MUTYH (21%), BRCA2 (8%), APC I1370K (8%), and Lynch Syndrome-associated (7%)." (PMID 40770526, 2025). "Other, less common, gene mutations include CHEK2, PALB2, CDH1, MLH1 (associatedwith Lynch syndrome), and RET." (PMID 38993971, 2024). "Out of 103 patients who underwent germline testing for Lynch syndrome, 19 (18.4%) showed a mutation in MMR genes with pathogenic or likely pathogenic significance and 8 (7.8%) in other CRC-associated genes (APC, CHEK2, MUTYH)." (PMID 39457591, 2024). "In our patient population meeting genetic test criteria for HBOC or Lynch syndrome, 12.5% of patients were found to have a pathogenic mutation, with the most common being in BRCA1/2 followed by MUTYH and CHEK2." (PMID 38136308, 2023). "Other genes, such as CHEK2, ATM, and PALB2 and Lynch syndrome genes, are also implicated in ovarian cancer." (PMID 32127576, 2020). "Furthermore, a combined 27% of participants who had genetic testing reported a mutation in BRCA1 (12%), BRCA2 (7%) or in another OC gene (8%; most commonly RAD51C/D, CHEK2 and the Lynch Syndrome genes)." (PMID 35621661, 2022). "PVs in BRCA1, but not BRCA2, PALB2, ATM, CHEK2, or Lynch syndrome genes, were associated with elevated RS on multivariable analysis (P < .001)." (PMID 33426465, 2021). "After removing the 8 other patients with CHEK2 mutations and all 11 patients in whom only 1 MUTYH mutation was identified, the number of patients with actionable mutations decreased to 42 (7.2%), with over half of these occurring in Lynch syndrome genes." (PMID 24506336, 2014). "Thirty-nine patients (2%) were identified as carriers of a PV in an autosomal dominant clinically actionable hereditary breast and ovarian cancer (HBOC)-related or Lynch syndrome gene, most frequently, BRCA2 (6/39; 15.4%), PALB2 (8/39; 20.5%), CHEK2 (10/39; 25.6%), and PMS2 (5/39; 12.8%)." (PMID 37861889, 2024). "Of 20 patientsinitially referred for Lynch syndrome, 3 had PV/LPVs on retesting, and noneultimately had this condition (CHEK2, MITF, MUTYH heterozygote,n = 1 each)." (PMID 34545504, 2022).
Lynch syndrome (continued). "Although CHEK2 is not a mismatch repair gene (MMR), mutations of this gene could be responsible for some cases of Lynch syndrome." (PMID 32283892, 2020).
bladder cancer (29 papers, 2008 to 2025). "Another report on 98 patients with bladder cancer showed that mutations in DNA repair genes (CHEK2, ERCC5, GEN1, MLH1, PALB2, RAD50, RAD51B and RECQL4) are associated with an unfavorable cancer prognosis and 22% of patients had a mutation." (PMID 35395863, 2022). "We observed a potentially protective effect of CHEK2 mutations on survival for patients with stage T1 bladder cancer." (PMID 34499690, 2021). "We noticed that CHEK2 missense mutations were more common among patients with low grade invasive bladder cancer and in patients with stage Ta." (PMID 34499690, 2021). "Our study revealed that any mutation in CHEK2 occurs more often among patients with bladder cancer with stage Ta and stage T1 disease." (PMID 34499690, 2021). "Our investigations revealed that any mutation in CHEK2 occurs more often among patients with stage Ta bladder cancer (OR = 2.0; 95% CI 1.19–3.47; p = 0.01) and less often in patients with stage T1 disease (OR = 0.31; 95% CI 0.12–0.78; p = 0.01)." (PMID 34499690, 2021). "Among patients with bladder cancer with stage Ta disease, the OR for any mutation in CHEK2 was 2.0 but for those with stage T1 disease, the OR was 0.3." (PMID 34499690, 2021). "To validate and extend our earlier findings we evaluated the prevalence of four commons CHEK2 mutations among 1016 patients with bladder cancer." (PMID 34499690, 2021). "Survival of patients with bladder cancer; by variant alleles of CHEK2." (PMID 34499690, 2021). "Clinical characteristics of bladder cancers; by variant alleles of CHEK2." (PMID 34499690, 2021). "The only CHEK2 mutation shown was described in a family with PrC, BC and bladder cancer." (PMID 33710808, 2021). "DNA damage which was observed through the interaction of 19-BJB with nucleotide chains and affected DNA repair resulted in the activation of checkpoint kinase 1 (Chk1) and checkpoint kinase 2 (Chk2) in bladder cancer cell lines." (PMID 33724994, 2021). "In bladder cancer cells treated with nimbolide, the G2/M phase cell cycle was arrested via the checkpoint kinase 2 (Chk2)/Cdc25C and Chk2/p21WAF1-related cyclin B1/Wee1 pathway." (PMID 33996570, 2021). "Of the missense variants examined in fishing cat gene orthologs for human bladder cancer risk genes, DNA damage repair pathway genes BRCA1/2, CHEK2, and ATM all showed higher missense variant prevalence in the cohort; however, only BRCA2 showed a skewed distribution in TCC over healthy cats." (PMID 38580653, 2024). "We observed a possible increased survival in the subgroup of patients with stage T1 bladder cancer with CHEK2 mutations but this was not statistical significance." (PMID 34499690, 2021). "The 10-year survival for all CHEK2 mutation carriers with bladder cancer was 33% and for non-carriers 11% (p = 0.15)." (PMID 34499690, 2021). "Herein we found no impact of CHEK2 mutations on survival from patients with cancer of bladder or kidney regardless of their age, smoking status, cancer family history and sex." (PMID 34499690, 2021). "However, we observed a possible increased survival in the subgroup of patients with stage T1 bladder cancer with CHEK2 mutations but this did not meet statistical significance (HR = 0.14; 95% CI 0.02–1.04; p = 0.055)." (PMID 34499690, 2021). "However, we observed a possible increased survival in the subgroup of patients with stage T1 bladder cancer with CHEK2 mutations but it was not statistical significance, and more patients would need to be studied to draw conclusions." (PMID 34499690, 2021).
Li-Fraumeni syndrome (27 papers, 2007 to 2026). "CHEK2 was originally described as a variant of Li-Fraumeni syndrome, but has been associated with several cancer types including other lymphoid malignancies." (PMID 41495781, 2026). "The first CHEK2 germline PV/LPVs identified have been associated with the Li-Fraumeni syndrome; subsequently, this association has been questioned because of phenotype differences among LFS patients and CHEK2 PV/LPV carriers." (PMID 32046255, 2020). "One previously published variant (1422delT) of the functional CHEK2 gene, was thought to predispose to Li-Fraumeni syndrome, but subsequently was shown to be the genomic sequence of a CHEK2 duplicon." (PMID 18831734, 2008). "CHEK2, a protein kinase activated in response to DNA damage, is involved in cell cycle arrest, and heterozygous germline mutations in this gene have been reported in patients with Li-Fraumeni syndrome-2." (PMID 38136276, 2023). "Implicated in Li-Fraumeni syndrome, known to increase the risk of developing several types of cancer including breast, the CHEK2: c.433G > A variant is expected to result in a misfolded protein that would be targeted for degradation via the ubiquitin-proteosome pathway." (PMID 27067391, 2016). "CHEK2 was originally suggested to be a high-risk gene for the Li Fraumeni syndrome." (PMID 17705858, 2007). "CHEK2 has previously been excluded as a major cause of Li-Fraumeni syndrome (LFS)." (PMID 19338683, 2009). "This cytosine deletion at nucleotide 1100 of CHEK2 sequence was also identified in two Finnish families with atypical Li-Fraumeni syndrome due to the lack of sarcomas or childhood cancers." (PMID 24986639, 2014).
leukemia (25 papers, 2007 to 2025). A malignant (clonal) hematologic disorder, involving hematopoietic stem cells and characterized by the presence of primitive or atypical myeloid or lymphoid cells in the bone marrow and the blood. "However, evidence supporting the relationship between CHEK2 variants and the risk of leukemia is still limited." (PMID 34771502, 2021). "CHEK2 is known to interact with several proteins that affect leukemia-specific pathways, such as KMT2D and FOXM1, but this remains to be explored further." (PMID 40335619, 2025). "We further demonstrate that clinically used SF3B1 inhibitors synergize with CHEK2 inhibitors and chemotherapeutic drugs to block leukemia growth." (PMID 35061527, 2022). "6/11 patients carried a prioritized VUS in CHEK2, and three of them developed a B-precursor leukemia." (PMID 33840814, 2021). "While DDR protein activation was not discernable from the mRNA GEP studies, several other reports note connections between leukemia and abnormalities in activated DDR proteins such as CHEK2.pT68 and CHEK1.pS345." (PMID 36982970, 2023). "These included CDH1-Blepharocheilodontic (BCD) Syndrome, CHEK2-osteosarcoma, NF1-leukemia, and NF1-pulmonary stenosis." (PMID 33959510, 2021). "Neither the leukaemia nor the Wilms tumour harboured a second hit in the recessive cancer gene CHEK2 but both tumours had gain of chromosome 18q, which is not a common copy number driver in either cancer." (PMID 39665570, 2025).
gastric cancer (24 papers, 2011 to 2026). A primary or metastatic malignant neoplasm involving the stomach. "CRC often recurs, particularly in patients with CHEK2 mutations, while gastric cancer was found to be frequent in individuals with CDH1 mutations." (PMID 40649708, 2025). "In our patient, who has giant cell glioblastoma, the CHEK2 mutation was inherited from their father, who had gastric cancer and renal cell carcinoma." (PMID 39411129, 2024). "The CHEK2 mutation was inherited from the patient’s father, who had a history of gastric cancer and renal cell carcinoma." (PMID 39411129, 2024). "A CHEK2 mutation was also identified to predispose to gastric cancer (OR = 1.6, p = 0.004), particularly in young-onset cases (OR = 2.1, p = 0.01)." (PMID 33959510, 2021). "Furthermore, some gene-disease associations are not found in any genetic resource, such as the association of CHEK2 with gastric cancer, which has been established with high likelihood in the literature." (PMID 33959510, 2021). "In addition to BC, CHEK2 PVs/LPVs have also been associated with other cancers, including prostate, colorectal, and gastric cancers." (PMID 32365798, 2020). "Among 40 females with BC and gastric cancer, 10 had PVs: BRCA2 (n = 3, 7.5%, 95% CI 2.0–21.5%) was the most frequent, followed by PALB2 (n = 2, 5.0%, 95% CI 0.9–18.2%) and CHEK2 (n = 2, 5.0%, 95% CI 0.9–18.2%)." (PMID 36856935, 2023). "The age- and sex-adjusted hazard ratio for CHEK2/1100delC heterozygotes compared with noncarriers was 5.76 (95% CI: 2.12-15.6) for gastric cancer and 3.61 (95% CI: 1.33-9.79) for kidney cancer." (PMID 33959510, 2021).